FGF8 (fibroblast growth factor 8)
Diseases named in the same sentence as FGF8 in open-access papers (continued):
Sharing a sentence is not in itself a finding about the gene and the disease.
oral squamous cell carcinoma (3 papers, 2021 to 2023). "FGF8 expression is elevated in oral squamous cell carcinoma tissues, and treatment of oral squamous cell carcinoma cell lines with FGF8 promoted cell migration, invasion, and EMT." (PMID 33801580, 2021). "Besides, FGF8 also shows a high expression in oral squamous cell carcinoma tissues, and it regulates the epithelial-mesenchymal transition and induces an invasive phenotype in oral squamous cell carcinoma cells." (PMID 36629518, 2023).
osteoarthritis (3 papers, 2008 to 2022). A noninflammatory degenerative joint disease occurring chiefly in older persons, characterized by degeneration of the articular cartilage, hypertrophy of bone at the margins and changes in the synovial membrane. "Recent studies have shown that the progression of osteoarthritis is related to the disorder of cellular metabolism, and FGF‐8 is involved in cartilage catabolic metabolism, which can be regarded as a potential therapeutic target for osteoarthritis." (PMID 35001536, 2022). "A possible effect of FGF8 in osteoblast proliferation and differentiation was described and an involvement of FGF8 together with BMPs and inflammatory cytokines in both RA and osteoarthritis (OA) was suggested." (PMID 33774802, 2021). "The aim of the present study was to clarify the role of FGF8 in animal models of osteoarthritis (OA)." (PMID 18699993, 2008). "FGF‐8 can promote angiogenesis and there is angiogenesis in joint inflammation such as osteoarthritis, so we speculated that when FGF‐8, especially FGF‐8B, is overexpressed, it may potentially promote the occurrence and development of joint inflammation." (PMID 35001536, 2022). "However, the specific molecular mechanisms, including the downstream signal transduction pathways activated by FGF‐8 in the progression of osteoarthritis and the specific binding of FGF receptor proteins, still require further investigation." (PMID 35001536, 2022). "FGF‐18 in osteoarthritis is different from FGF‐8 because it mainly protects cartilage." (PMID 35001536, 2022). "FGF8 may therefore participate in the degradation of cartilage and exacerbation of osteoarthritis." (PMID 18699993, 2008).
Arthritis (2 papers, 2008 to 2022). Inflammation of a joint. "In the monoiodoacetic acid-induced arthritis model, anti-FGF8 antibody reduced ECM release into the synovial cavity." (PMID 18699993, 2008). "The present study provides new and interesting findings about the role of FGF8 in joint inflammation." (PMID 18699993, 2008). "Anti-FGF8 antibody inhibited release of S-GAG in the MIA-induced arthritis model." (PMID 18699993, 2008). "Anti-FGF8 antibody attenuates the destruction of cartilage in the MIA-induced arthritis model." (PMID 18699993, 2008). "Anti-FGF8 antibody not only reduced cartilage degradation induced by the injection of FGF8 in the joints, but also decreased cartilage degradation in the MIA-induced rat arthritis model." (PMID 18699993, 2008).
cervical cancer (2 papers, 2017 to 2022). A primary or metastatic malignant neoplasm involving the cervix. "Moreover, hypermethylation of LYPD2 and SHE were associated with poor overall survival (OS); hypermethylation of FGF8 and HSPA6 were associated with poor progression free survival (PFS) in patients with cervical cancer." (PMID 29029430, 2017).
deafness (2 papers, 2016 to 2022). An inherited or acquired condition characterized by the complete loss of the ability to hear from one or both ears. "Firstly, some of the genes are independently known to be involved in hearing, such as Fgf8, Slc26a5 (prestin), Pou4f3 and Gfi19, 10, 39, 40, suggesting that other genes in the network may also underlie deafness." (PMID 26988146, 2016).
lymphoma (2 papers, 2019 to 2023). A malignant (clonal) proliferation of B- lymphocytes or T- lymphocytes which involves the lymph nodes, bone marrow and/or extranodal sites. "Noteworthy, FGFR1 can be activated via various ligands (FGF1-6, FGF-8, 19,21, and 23), and previous studies of leukemia and lymphoma cells show higher expression of FGF2 ligands." (PMID 37598282, 2023).
microcephaly (2 papers, 2023 to 2024). A congenital or acquired developmental disorder in which the circumference of the head is smaller than normal for the person's age and sex. "Simultaneous inactivation of Cubn and FgfR3 worsens the microcephaly phenotype: the addition of the deficits indicates that Cubn and FgfR3 are partners in Fgf8 signaling at these early stages." (PMID 37372994, 2023). "When these two BMP antagonists are inactivated simultaneously by bilateral electroporation with double-stranded RNAs, and then grafted onto a non-transfected host embryo, these experiments lead to a drastic reduction of Fgf8 expression in the ANR, and result in microcephaly." (PMID 37372994, 2023).
polymicrogyria (2 papers, 2015 to 2017). A developmental brain abnormality characterized by an excessive amount of small convolutions on the surface of the brain and cognitive dysfunction. "We have shown that FGF8-transfected ferrets have polymicrogyria, megalencephaly and subependymal heterotopia, which are common features of human TD patients." (PMID 26482531, 2015). "sFGFR3 did not seem to affect the number of the gyri, though FGF8 increased it, leading to polymicrogyria." (PMID 29132503, 2017). "Because we expressed FGF8 only in the nervous system, our study using TD ferrets directly indicate that as in the case of megalencephaly, FGF signaling in the brain is responsible for polymicrogyria." (PMID 26482531, 2015).
rectal cancer (2 papers, 2019). A primary or metastatic malignant neoplasm that affects the rectum. "In this study, protein levels of FGF8 and Survivin were strongly correlated with therapy response in a cohort of 43 rectal cancer patients indicating that they are promising candidates as predictive markers for nRCT response." (PMID 30276721, 2019). "The results of this study suggest that FGF8 and Survivin contribute to radiation resistance in rectal cancer and may serve as markers to select patients who may not benefit from neoadjuvant radiotherapy." (PMID 30276721, 2019).
thyroid (2 papers, 2018 to 2021). "Wendl and colleagues (2007) reported that, during zebrafish somitogenesis, fgf8 is detectable in cardiac mesoderm, adjacent the developing anterior foregut endoderm, and that fgf8 aceti282a mutants exhibit thyroid dysgenesis." (PMID 34149617, 2021). "It is envisaged that lack of Fgf8 reduces the number of progenitors committed to a thyroid fate, which might at least partly explain thyroid dysgenesis in the absence of Tbx1." (PMID 29361553, 2018).
22q11.2 deletion syndrome (1 paper, 2023). 22q11.2 deletion syndrome (DS) is a chromosomal anomaly which causes a congenital malformation disorder whose common features include cardiac defects, palatal anomalies, facial dysmorphism, developmental delay and immune deficiency. "Although human FGF8 does not localize to 22q11, Fgf8 deficiency in mice generates many features of 22q11.2 deletion syndromes." (PMID 37287454, 2023).
anodontia (1 paper, 2012). Anodontia is an extreme developmental dental anomaly characterized by the complete absence of all teeth. "Therefore, the presence of agnathia and anodontia observed in HhatCreface/Creface embryos correlates with the loss of Fgf8 and Bmp4 activity in the pharyngeal arch ectoderm." (PMID 23055936, 2012).
autism (1 paper, 2014). Persistent deficits in social interaction and communication and interaction as well as a markedly restricted repertoire of activity and interest as well as repetitive patterns of behavior. "It is also a partner of FGF8 [FGF8 is one of FOXP2 as targets], a protein involved in the regionalization of brain tissues in mammals], and of SMAD9 [the locus of the gene, AUTS3, is linked to autism; MAD proteins usually regulate cell proliferation and differentiation]." (PMID 24772099, 2014).
bladder cancers (1 paper, 2008). "FGF pathway genes, including FGF3, FGF4 and FGF8, are common targets of MMTV integration and FGFR3 mutations have been reported in 41% of bladder cancers." (PMID 18840272, 2008).
cartilage disease (1 paper, 2022). Softening and degeneration of the CARTILAGE. "At present, the relationship between FGF‐8 and cartilage diseases has been lucubrated, aiming to provide potential guidance for the diagnosis and treatment of cartilage diseases in future." (PMID 35001536, 2022). "However, the molecular mechanism of FGF‐8 in normal or pathological cartilage remains unclear, and thus, FGF‐8 represents a novel exploratory target for studies of chondrocyte development and cartilage disease progression." (PMID 35001536, 2022). "Thus, in this review, we summarize the background of FGF‐8 and its receptors (FGFRs) in articular cartilage development, homeostasis and related cartilage diseases, discuss the current research of OA and cartilage injury based on FGF‐8, and emphasize the future challenges in this field." (PMID 35001536, 2022). "Considering the structural homology of FGF‐18 and FGF‐8, understanding the role of FGF‐18 in cartilage diseases may provide some instructions for us to better understand FGF‐8." (PMID 35001536, 2022).
choanal atresia (1 paper, 2012). Choanal atresia (CA) is a congenital anomaly of the posterior nasal airway characterized by the obstruction of one (unilateral) or both (bilateral) choanal aperture(s), with clinical manifestations ranging from acute respiratory distress to chronic nasal obstruction. "Developmental defects of GnRH neurons and the olfactory bulb are associated with hyposmia, rarely associated with the clinical phenotypes of synkinesia, cleft palate, ear anomalies, or choanal atresia, and may be due to mutations of KAL1, FGFR1/FGF8, PROKR2/PROK2, or CHD7." (PMID 22229029, 2012).
chondrosarcoma (1 paper, 2024). A malignant cartilaginous matrix-producing mesenchymal neoplasm arising from the bone and soft tissue. "To investigate whether FGF4, FGF8, and FGF9 induce differential signaling via FGFR1c (referred to as FGFR1 here), we used rat chondrosarcoma (RCS) chondrocytes, an immortal chondrocyte cell line used to model proliferating chondrocytes in the developing limb." (PMID 38568193, 2024).
coloboma (1 paper, 2017). An abnormality in which a part of a structure in one or both eyes is missing. "We previously reported evidence for reduced Fgf8 expression and FGF signaling in the mid-hindbrain region of embryos heterozygous for Chd7, the gene mutated in CHARGE (Coloboma, Heart defects, choanal Atresia, Retarded growth and development, Genitourinary anomalies and Ear defects) syndrome." (PMID 29046629, 2017).
colon cancer (1 paper, 2021). "In the GCSC database, the methylation levels of FGF8, NOG, TCF15, TWIST1, TBX5, SIX2, and TIAM1 are higher in colon cancer." (PMID 34526059, 2021).
cyst (1 paper, 2018). A sac-like closed membranous structure that may be empty or contain fluid or amorphous material. "The present research work investigated the expression of BMP4 and FGF8 in odontogenic tumors (OT) and cyst as well as developing tooth germs to elucidate their roles." (PMID 30079292, 2018).
esophageal cancer (1 paper, 2024). A primary or metastatic malignant neoplasm involving the esophagus. "This study investigates the role of three specific proteins—FGF8, ALK, and EML4—in predicting the prognosis of patients with esophageal squamous cell carcinoma (ESCC), a common type of esophageal cancer." (PMID 39518064, 2024).
esophageal squamous cell carcinoma (1 paper, 2024). Esophageal squamous cell carcinoma (ESCC) is a type of esophageal carcinoma (EC) that can affect any part of the esophagus, but is usually located in the upper or middle third. "The aim of this study was to examine the prognostic role of FGF8, ALK, and EML4 in esophageal squamous cell carcinoma (ESCC)." (PMID 39518064, 2024).
esophagogastric junction adenocarcinoma (1 paper, 2023). "As reported, FGF8 is highly expressed in esophagogastric junction adenocarcinoma, and is expected to be a candidate gene for the prognostic factor for this cancer." (PMID 36629518, 2023).
glaucoma (1 paper, 2023). Increased pressure in the eyeball due to obstruction of the outflow of aqueous humor. "Cluster 2 also differentially expressed glaucoma gene CYP1B1, morphogen-encoding genes LEFTY2, FGF9, and FGF8." (PMID 37665325, 2023).
Hallux valgus (1 paper, 2021). Lateral deviation of the great toe (i.e., in the direction of the little toe). "Then we examined the mRNA levels of FGF family, FGF1, FGF4, FGF7, FGF8, FGF9 and found the high mRNA level of FGF9 in hallux valgus patients." (PMID 33456347, 2021).
hearing loss (1 paper, 2017). "In a clinical sense, recognizing those IHH genes and associated phenotypes may improve our diagnostic capabilities by enabling us to prioritize the screening of particular gene(s) such as synkinesia (ANOS1), dental agenesis (FGF8/FGFR1) and hearing loss (CHD7)." (PMID 29280744, 2017).
Holt-Oram syndrome (1 paper, 2025). Holt-Oram syndrome (HOS) is the most common form of heart-hand syndrome and is characterized by skeletal abnormalities of the upper limbs and mild-to-severe congenital cardiac defects. "Interestingly, left-biased limb defects were detected in Holt-Oram syndrome patients, while mice with Fgf8 deficiency also showed a stronger defect on the left side." (PMID 39906257, 2025).
Hypoglycemia (1 paper, 2020). A decreased concentration of glucose in the blood. "In the oxidative stress marker panel, only PTGS2 differed between T2DM and controls (p < 0.0001), and comparison of baseline to hypoglycemia in T2DM subjects showed fibroblast growth factor 8 (FGF8) (p < 0.0001) was significantly different, after multiple testing correction." (PMID 32179763, 2020).
insulin-resistant (1 paper, 2025). "Conversely, EGFR and FGF8 were no longer significant indicating that these are dependent on IR, in accord with the literature for EGFR, while FGF8 modulation by insulin resistance is a novel finding." (PMID 40072105, 2025).
Intellectual disability (1 paper, 2024). "ZIC1, which was significantly up-regulated in FGF8-treated organoids, is implicated in complex syndromes involving cortical, callosal, and cerebellar malformations associated with intellectual disability." (PMID 39485283, 2024).
invasive carcinoma (1 paper, 2002). A carcinoma that is not confined to the epithelium, and has spread to the surrounding stroma. "In sections where normal elements of breast tissues could be seen adjacent to invasive carcinoma, higher levels of FGF8 staining were consistently seen in carcinoma elements compared to normal elements." (PMID 11953856, 2002).
invasive lobular carcinoma (1 paper, 2002). "We therefore compared the levels of FGF8 staining in groups of invasive ductal and invasive lobular carcinoma." (PMID 11953856, 2002).
juvenile rheumatoid arthritis (1 paper, 2008). "Further studies are required of whether FGF8 has a physiological function in maturing of joints and diseases in children such as juvenile rheumatoid arthritis." (PMID 18699993, 2008).
lobular carcinoma of the breast (1 paper, 2002). "Transgenic mice overexpressing FGF8 under an MMTV promoter have been reported to produce lobular carcinoma of the breast." (PMID 11953856, 2002).
lung carcinoma (1 paper, 2023). "FGF8 activates FGFR1 by directly binding to it, which aggravates lung cancer and results in the phosphorylation of ERK1/2." (PMID 36629518, 2023). "The fibroblast growth factor 8 (FGF8)/FGF receptor 1 (FGFR1)/extracellular signal-regulated kinase 1/2 (ERK1/2) axis functions in the tumorigenesis in various tumors, including lung cancer, and its role involves involved in the invasion, metastasis and progression of non-neoplastic lesions." (PMID 36629518, 2023).
medulloblastoma (1 paper, 2014). A malignant, invasive embryonal neoplasm arising from the cerebellum. "Known developmental repressors of OTX2 in the hindbrain include Gbx2 and Fgf8; however, these genes are rarely expressed in established medulloblastomas." (PMID 25198066, 2014).
metastatic tumor (1 paper, 2020). "Collectively, these studies convincingly underscore the importance of SP8-induced FGF8 in metastatic disease, as we have shown here for HB." (PMID 32824198, 2020). "Of note, we had one patient with non-metastatic HB at the initial diagnosis, but showed high SP8 and FGF8 levels in the primary tumor suggestive of metastatic disease, who intriguingly developed a lung metastasis eight months after tumor resection." (PMID 32824198, 2020). "However, as we have analyzed only one paired primary/metastatic tumor, the underlying mechanism for SP8 and FGF8 expression returning to normal in the metastasis, remains uncertain." (PMID 32824198, 2020). "In summary, we identified SP8 and FGF8 as key players in aggressive traits of HB and propose SP8 inhibiting drugs as a new effective treatment strategy especially for metastatic tumors." (PMID 32824198, 2020).
nasopharyngeal carcinoma (1 paper, 2017). A carcinoma arising from the nasopharyngeal epithelium. "FGF8 is a member of the fibroblast growth factor (FGF) family is involved in tumor growth and invasion in nasopharyngeal carcinoma." (PMID 29029430, 2017).
neuronal tumor (1 paper, 2012). Neuronal brain tumors are an uncommon group of central nervous system tumors that arise from cells with neuronal differentiation. "Amsterdam reported the relationship between fgf8 misregulation and neuronal tumors in Zebrafish." (PMID 23217062, 2012).
odontogenic cyst (1 paper, 2018). A cyst in the jaw that arises from tissues of tooth development. "In conclusion, the results suggest that BMP4 and FGF8 are expressed in different odontogenic cyst and tumors with varying intensity based on their expected behavior." (PMID 30079292, 2018).
omphalocele (1 paper, 2020). Omphalocele is an embryopathy classified in the group of abdominal celosomias and is characterized by a large hernia of the abdominal wall, centered on the umbilical cord, in which the protruding viscera are protected by a sac. "The results we have obtained thus far present something of a conundrum: how does the loss of Fgf8 and Fgf17 in the PSM cause omphalocele at E13.5 and later?" (PMID 32907848, 2020). "Consistent with the hypothesis that omphalocele is multifactorial in origin, we find that Fgf8 and Fgf17 are needed in the PSM whereas Fgf18 is required in the somites." (PMID 32907848, 2020). "In Cited1Cre;Fgf8f/Δ;Fgf17Δ/Δ;Fgf18f/+ embryos, the omphalocele incidence was very infrequent and equivalent to controls (one individual in each genotype), suggesting that the loss of Fgf8 expression in the somites does not cause a VW closure defect and therefore the Fgf8 requirement is in the PSM." (PMID 32907848, 2020). "From these results we conclude that the requirement for Fgf8 expression is in the PSM; the hypothesis that Fgf8 is required in the PSM is further supported by the fact that loss of Fgf17 in TCre;Fgf8f/Δ mutants promoted omphalocele, and Fgf17 is expressed in the PSM but not the somites." (PMID 32907848, 2020).
Onset (1 paper, 2019). The age group in which disease manifestations appear. "In particular, in three patients presenting with mild, adult-onset disease we found variants (PROKR2 R85H, FGF8 P26L, and HS6ST1 R382W) already reported to impair protein activity in several functional characterization or to segregate with the phenotype, or both." (PMID 30669598, 2019).